TSC2 (TSC complex subunit 2)
Diseases named in the same sentence as TSC2 in open-access papers (continued):
Sharing a sentence is not in itself a finding about the gene and the disease.
Infertility (4 papers, 2012 to 2025). "Sustained activation of mTOR in germ cells by genetic ablation of the Pten/Tsc1/Tsc2 causes untimely recruitment of primordial follicles leading to premature ovarian failure and infertility." (PMID 27036037, 2016). "Oocyte-specific loss of TSC1 or TSC2 leads to premature ovarian failure and infertility in mice." (PMID 22916036, 2012).
Kidney Cyst (4 papers, 2015 to 2024). Abnormal fluid filled sac within the kidney, either acquired or congenital. "While similar patterns were observed for kidney cysts from children above 5 years, we also found children under 5 to have relatively higher rates comparable to those of children aged 15 years (2.31 vs. 2.82 mm/year), although most data were from children with TSC2 mutations." (PMID 38832977, 2024). "Three children had TSC2/PKD1 contiguous gene deletion syndrome, which may provide a slight bias to the results in terms of overall CKD risk and kidney cyst burden." (PMID 38483608, 2024). "Recent studies on kidney cysts in various mouse models of TSC, including mice with principal cell- or pericyte-specific inactivation of TSC1 or TSC2, have identified a unique cystogenic mechanism." (PMID 38028758, 2023). "The prevalence of kidney cysts in TSC alone is between 30 and 50 %, more frequent in TSC2 than TSC1, especially when the TSC2 gene harbours a nonsense or frameshift mutation." (PMID 26077033, 2015).
liver hemangioma (4 papers, 2014 to 2025). A hemangioma arising from the liver. "This is in line with the lack of tumor-inhibiting properties of atorvastatin in a mouse model of TSC2-related liver hemangioma, but not with data obtained with a MYC-driven HCC mouse model where atorvastatin acted as a tumor-preventive compound." (PMID 25319454, 2014).
metastatic tumor (4 papers, 2020 to 2024). "Moreover, a recent genomic landscape of 10,000 metastatic tumor revealed that TSC2 missense mutations were presented in 294 patients with different types of cancer, but only one mutation was identified in 93 patients with PTC-related metastasis." (PMID 34249677, 2021). "Mutations in both TSC2 and STK11 were found exclusively in metastatic samples and are possibly associated with the development of metastatic disease or resistance to therapy." (PMID 32811538, 2020).
pneumothorax (4 papers, 2016 to 2025). Abnormal presence of air in the pleural cavity. "In LAM, abnormal proliferation of smooth muscle-like cells and destruction of the lung parenchyma caused by TSC1 or TSC2 gene mutations increase the fragility of lung tissue and the risk of pneumothorax." (PMID 39934870, 2025). "In general, stop-gain mutation in TSC2 was related to a higher pneumothorax prevalence." (PMID 36117164, 2022). "Stop-gain mutations in TSC2 were related to a higher rate of pneumothorax occurrence." (PMID 36117164, 2022). "Moreover, stop-gain mutation in TSC2 was associated with a high rate of pneumothorax." (PMID 36117164, 2022). "TSC2 mutation was significantly related to a shorter 6MWD (p < 0.05), and a higher percentage of VEGF-D over 800 pg/mL (p < 0.05); stop-gain mutation was significantly related to a higher prevalence of pneumothorax." (PMID 36117164, 2022).
premature ovarian failure (4 papers, 2012 to 2020). "In early adulthood of mice, the TSC2-deficient in oocytes depletes follicles and results in premature ovarian failure." (PMID 33218349, 2020). "In ovaries, specific deletion of Tsc1 or Tsc2 in oocytes leads to primordial follicle depletion, causing premature ovarian failure." (PMID 23335988, 2013). "In the ovary, oocyte specific disruption of either Tsc1 or Tsc2 leads to global activation of primordial follicles at the time of puberty, resulting in early follicle depletion and premature ovarian failure (POF)." (PMID 23335988, 2013).
anaplastic thyroid cancer (3 papers, 2016 to 2026). "A cBioPortal query (2285 cases) found TSC1 alterations in 2% and TSC2 in 1%, mostly deletions, enriched in poorly differentiated and anaplastic thyroid carcinomas." (PMID 41518426, 2026). "Similarly, one anaplastic thyroid cancer patient who showed sensitivity to everolimus, revealed a nonsense mutation in TSC2, a negative regulator of mTOR." (PMID 26859683, 2016).
brain malformations (3 papers, 2018 to 2025). "Notably, we included well-known and common causes of IS (trisomy 21, TSC2) and children with brain malformations and neurometabolic diseases which are typically excluded from gene discovery investigations." (PMID 29518120, 2018). "It is known that activating the mTOR pathway causes the epileptogenicity of brain malformations, specifically FCD, TS, and HS, which is supported by our finding that 80% of APEs with TSC1 or TSC2 variants had such malformations." (PMID 31875159, 2019). "Eight of ten APEs (80%) with TSC1 or TSC2 variants but none of the three APEs with DEPDC5 variants had brain malformations including FCD, HS, or TS." (PMID 31875159, 2019).
breast tumors (3 papers, 2015 to 2022). "By analyzing a gene expression dataset of breast tumors that metastasize to the lung, we identified genes negatively correlated with TSC2 (Pearson’s correlation coefficient (PCC) < 0, and one‐sided P < 0.05)." (PMID 34378323, 2021). "Next, analysis of an independent dataset from primary breast tumors also showed low TSC1 and TSC2 expression to be specifically associated with lung metastasis." (PMID 26167915, 2015). "Invasive breast tumors have lower protein expression of TSC1 and TSC2 compared to the normal mammary epithelium." (PMID 35608730, 2022).
colitis (3 papers, 2018 to 2024). Inflammation of the colon. "Collectively, these results indicated that excessive activity of mTORC1 induced by Tsc2 ablation in CECs increases the susceptibility of mice to DSS-induced colitis." (PMID 32796887, 2020). "We therefore tested the susceptibility of Tsc2 CKO mice to DSS-induced colitis." (PMID 32796887, 2020). "The increased susceptibility of Tsc2 CKO mice to DSS-induced colitis might thus be attributable to suppression of Wnt signaling and the reduced number of CSCs in these animals." (PMID 32796887, 2020). "Given that proper regulation of autophagy is thought to be important for protection against colitis in humans and mice, the increased susceptibility of Tsc2 CKO mice to DSS-induced colitis also might be attributable to dysregulation of autophagy." (PMID 32796887, 2020). "Finally, Tsc2 CKO mice manifested increased susceptibility to dextran sulfate sodium–induced colitis." (PMID 32796887, 2020). "Finally, we found that Tsc2 CKO mice manifested an increased susceptibility to DSS-induced colitis." (PMID 32796887, 2020). "At 3 days after the onset of DSS treatment, hematoxylin–eosin staining of the colon also showed that Tsc2 CKO mice developed more severe colitis compared with control mice." (PMID 32796887, 2020). "Interestingly, although Tsc2, an upstream regulator of mTOR signaling, has also been shown to regulate Notch, we could not find any evidence in our protein or gene expression data indicating that Notch signaling, in addition to mTOR signaling, is activated in the TCT model of colitis." (PMID 29596476, 2018).
cortical dysplasia (3 papers, 2013 to 2022). "We targeted the gene TSC2, which encodes a negative regulator of mTOR; somatic mutations in this gene have been shown to underlie certain focal cortical dysplasias in humans." (PMID 34969984, 2022). "As a proof of principle, we targeted TSC2 immediately before neuroectoderm formation, as mutations in this gene have been shown to underlie certain focal cortical dysplasias in humans." (PMID 34969984, 2022). "The areas of cerebral cortical dysplasia in the form of cortical tubers (CT) were prevalent in 42% and 80% of TSC1 and TSC2 patients, respectively." (PMID 35440050, 2022).
cystic lung disease (3 papers, 2020 to 2025). "Patients STLAM4, STLAM5, and STLAM7 did not carry the FGFR4 variant but exhibited cystic lung disease in the absence of detectable systemic TSC2 mutations." (PMID 40776927, 2025).
Down syndrome (3 papers, 2018 to 2024). "None of the enriched sets of pathways and functions associated with SCN1A was associated with the Down syndrome genes (DYRK1A, PSMG1, RCAN1, DSCR3, DSCR4) or with TSC2." (PMID 29518120, 2018). "IS was present in most of the children with pathogenic variants in CDKL5 (3/4) and TSC2 (5/7) and with Down syndrome (with or without karyotype confirmation of trisomy 21) (20/22)." (PMID 29518120, 2018). "Notably, there was little overlap in the compiled biological pathways between TSC2 and the Down syndrome genes." (PMID 29518120, 2018).
focal epilepsy (3 papers, 2019 to 2025). A seizure caused by a localized disorder. "In a female patient (E100), aged 3 months, presenting with subcortical and periventricular tubers, hypomelanotic nevi, focal epilepsy, and diminished eye contact, we identified a novel variant in the TSC2 gene (c.5068 + 2 T > C), Clinvar ID 165914071." (PMID 38328757, 2023). "The mTOR genes including DEPDC5, TSC1 and TSC2 have been associated with focal epilepsy, as was the case in our study in which the mTOR genes had the highest yield (13/32), although the yield was relatively low in some previous studies." (PMID 31875159, 2019). "Recent studies have linked mutations in several genes involved in the mTOR signaling pathway - such as TSC1, TSC2, MTOR, DEPDC5, NPRL2, and NPRL3 - to the development of focal epilepsies in affected individuals." (PMID 40546503, 2025).
hemimegalencephaly (3 papers, 2020 to 2021). "Interestingly, hemimegalencephaly may arise as a result of germline and second‐hit somatic mutation in TSC2, without any other organ symptoms of TSC." (PMID 34328682, 2021). "Although megalencephaly and hemimegalencephaly are not typical symptoms of TSC, the case reports confirm the involvement of the activation of the mTOR pathway in processes leading to brain overgrowth, similar to our studies with Tsc2+/− mice." (PMID 34576223, 2021).
Hyperinsulinemia (3 papers, 2011 to 2021). An increased concentration of insulin in the blood. "Nonfasting and fasting insulin levels at 8 weeks of HFD were also significantly reduced in TSC2-KOPlacenta mice compared with controls, suggesting lack of hyperinsulinemia development in these animals under HFD treatment." (PMID 34032632, 2021). "Therefore, one possible mechanism of metabolic health protection is that lack of hyperinsulinemia contributed to the prevention of weight gain in the TSC2-KOPlacenta mice." (PMID 34032632, 2021).
insulinoma (3 papers, 2011 to 2025). "Isolated islets from βTSC2−/− mice and TSC2 knockdown insulin 1 (INS-1) insulinoma cells treated with small interfering ribonucleic acid were used to investigate insulin secretion, ATP content and the expression of mitochondrial genes." (PMID 21886784, 2011). "This study analyzes the role of TSC2 acetylation levels in its translocation to the lysosome and the mitochondrial turnover in both mouse embryonic fibroblast (MEF) and in mouse insulinoma cells (MIN6) as a model of pancreatic β cells." (PMID 38822085, 2024).
Macrocephaly (3 papers, 2015 to 2024). Occipitofrontal (head) circumference greater than 97th centile compared to appropriate, age matched, sex-matched normal standards. "In addition, two children in our sample, one with a mutation in PTPN11, and the other with mutations in TSC2 and SRCAP, also exhibited macrocephaly (a structural anomaly)." (PMID 39350038, 2024).
neuroendocrine carcinoma (3 papers, 2020 to 2025). A malignant neuroendocrine neoplasm composed of cells containing secretory granules that stain positive for NSE and chromogranin.
Oncocytic Tumor (3 papers, 2021 to 2022). "TSC1 and TSC2 mutations occur in sporadic high-grade oncocytic tumor (HOT) of the kidney and eosinophilic vacuolated tumor (EVT) of the kidney." (PMID 34680979, 2021).
osteosarcoma (3 papers, 2021 to 2024). A usually aggressive malignant bone-forming mesenchymal neoplasm, predominantly affecting adolescents and young adults. "TSC2 and RB1 genes have been found to be mutated in acute T-cell lymphoid leukemia and osteosarcoma." (PMID 38672648, 2024). "In osteosarcoma, TRIM28 promotes the SUMOylation modification of VPS34 by forming a complex with PVT-1 (Plasmacytoma variant translocation-1), further enhancing the ubiquitination and degradation of TSC2, thereby enhancing the self-renewal and stem cell phenotype of osteosarcoma cells." (PMID 39100077, 2024).
uterine tumors (3 papers, 2022 to 2023). "Therefore, this impaired capacity to repair the DNA could lead to the loss of the wild-type TSC-2 allele in EDC-MMSCs, which would trigger the development of uterine tumors at a higher frequency in EDC-exposed Eker rats than unexposed." (PMID 37333266, 2023).
adenomyosis (2 papers, 2021 to 2024). The growth of endometrial tissue inside the muscular wall of the uterine corpus. "This loss of rhythmic LC3A expression in adenomyosis patients was linked to a decrease in TSC2 expression, which in turn would inhibit autophagy through the activation of the mTOR signaling pathway." (PMID 39768424, 2024). "Collectively, our results suggest that TSC2 controls endometrial epithelial cell migration and EMT by regulating mTOR1-autophagy axis activation and that hypo-expression of TSC2 in the endometrium might promote adenomyosis." (PMID 34395438, 2021). "However, whether TSC2 participates in adenomyosis via autophagy remains obscure." (PMID 34395438, 2021). "Here, we found that the expression of TSC2 in adenomyosis was significantly decreased than that in normal endometrium during the secretory phase." (PMID 34395438, 2021).
brain ischemia (2 papers, 2015 to 2025). Diminished or absent blood supply to the brain caused by obstruction (thrombosis or embolism) of an artery resulting in neurologic damage. "It has been proved, however, that Nampt regulates autophagy in neurons upon cerebral ischemia through the TSC2 Ser1387-TOR-S6K1 signaling pathway via aSIRT1-dependent manner." (PMID 25729215, 2015). "However, there has also been research elucidating that autophagy induced by regulation of the TSC2-mTOR-S6K1 signaling pathway promotes neuronal survival during cerebral ischemia." (PMID 25729215, 2015).
congenital heart defects (2 papers, 2019 to 2022). "However, to the best of our knowledge, no previous studies have investigated the role of the c.2639 + 1G > C splice site mutation in intron 22 of the TSC2 gene in the diagnosis of congenital heart disease." (PMID 30683072, 2019). "Gene analysis may be used for prenatal diagnosis for congenital heart disease via the molecular analysis of a splicing mutation (c.2639 + 1G > C) in the splice donor site of intron 22 of the tuberin (TSC2) gene in the mother and the fetus." (PMID 30683072, 2019). "This study marks the first empirical investigation of the co-morbidity between congenital heart defects (CHD), NDDs, and KDs in TSC1 and TSC2 patients." (PMID 35440050, 2022).
end-stage renal disease (2 papers, 2019 to 2023). "Several reports characterized TSC2/PKD1 CGS as a severe polycystic kidney growth with onset and end-stage renal failure at an early age." (PMID 31870441, 2019). "Obviously, the genetic diagnosis of TSC2/PKD1-CGS predicts the appearance of a more severe phenotype, and affected patients need improved attention with assistance to prepare for earlier occurring end-stage renal disease." (PMID 36979978, 2023). "The presence of TSC2 and PKD1 gene deletions should be considered in the clinical assessment of TSC in children with early-onset PKD and in all patients with ADPKD who develop end-stage renal failure prior to the fourth or fifth decade of life." (PMID 31870441, 2019).
endometrial tumors (2 papers, 2016 to 2024). "PTEN mutations are found in 10% of central nervous system and endometrial tumors, TSC1 mutations in 5%–6% of urinary tract and endometrial tumors, and TSC2 mutations in 4%–7% of gynecological, liver, and lung tumors." (PMID 38515456, 2024).
esophageal cancer (2 papers, 2007 to 2018). A primary or metastatic malignant neoplasm involving the esophagus. "But there is no related studies in esophageal cancer, so the PDX models with TSC2 mutation will provided a useful tool." (PMID 29370817, 2018).
ganglioglioma (2 papers, 2018 to 2025). A well differentiated, slow growing neuroepithelial neoplasm composed of neoplastic, mature ganglion cells and neoplastic glial cells. "In comparison with the control group, the frequency of TSC2 gene polymorphism was significantly elevated in gangliogliomas." (PMID 40662483, 2025).
head and neck squamous cell carcinoma (2 papers, 2021 to 2026). A squamous cell carcinoma that arises from any of the following anatomic sites: lip and oral cavity, nasal cavity, paranasal sinuses, pharynx, larynx, and salivary glands. "Moreover, neddylation of tuberous sclerosis complex 2 (TSC2) inactivates the mTOR pathway, enhancing migration, invasion, and EMT in head and neck squamous cell carcinoma (HNSCC)." (PMID 41540013, 2026).
heart failure (2 papers, 2020 to 2023). Inability of the heart to pump blood at an adequate rate to meet tissue metabolic requirements. "Cardiac-specific overexpression of TORC1 increases stress-induced heart failure, whereas overexpression of Tsc1 and Tsc2 prevents the age-related increase of stress-induced heart failure." (PMID 31884871, 2020).
hemangioma (2 papers, 2007 to 2022). A benign vascular lesion characterized by the formation of capillary-sized or cavernous vascular channels. "In particular, tsc1+/- or tsc2+/- mutant mice which are characterized by high level of mTOR-mediated phosphorylation of Eif4ebp1 and Rps6kb1, have hemangiomas with poorly developed vasculature that are prone to rupture." (PMID 17892597, 2007).
Hepatic steatosis (2 papers, 2024 to 2025). Steatosis is a term used to denote lipid accumulation within hepatocytes. "Hepatic IL-37d is physiologically involved in ALD and the rh-IL37d protein can greatly improve alcohol-induced hepatic steatosis via negatively modulating Rheb-mTORC1 signaling in a TSC2-independent manner in mice." (PMID 38907105, 2024). "Collectively, the protective effect of the rh-IL37d in alcohol-induced hepatic steatosis is dependent on the suppression of Rheb activity in a TSC2-independent manner." (PMID 38907105, 2024).
Hypoglycemia (2 papers, 2011 to 2024). A decreased concentration of glucose in the blood. "Based on our findings, we suggest that fetal hypoglycemia decreases fetal growth by the activation of AMPK and TSC2, which in turn inhibit mTORC1 signaling." (PMID 38194365, 2024).
immunodeficiencies (2 papers, 2023 to 2025). "To examine this, we injected B7-H3 knockdown and control Tsc2-deficient 105K cells into wild-type and Rag1−/− mice, which have a combined T and B cell immunodeficiency." (PMID 36869048, 2023).